GCG (glucagon)
Diseases named in the same sentence as GCG in open-access papers (continued):
Sharing a sentence is not in itself a finding about the gene and the disease.
Hypoglycemia (continued). "Similarly, glucagon responses to hypoglycemia were amplified and peaked at a higher plasma glucose level in the group receiving ICV catalase, consistent with a shifted threshold for counterregulatory responses in this group." (PMID 27740870, 2016). "Similarly, the VMH functions as a nutrient sensor and has been shown to respond to declining nutritional conditions such as hypoglycemia by inhibiting insulin production and stimulating glucagon and catecholamines release." (PMID 27598259, 2016). "Acutely, the patient’s hypoglycemia resolved with dextrose and glucagon infusion." (PMID 27905899, 2016). "Diabetic patients often show exaggerated glucagon secretion that contributes to hyperglycemia, but also a reduced glucagon response to hypoglycemia, which may become fatal due to the brain’s strong glucose dependence." (PMID 27539300, 2016). "The risk of hypoglycaemia may be further reduced with the use of bihormonal (also known as dual-hormone) closed-loop systems delivering subcutaneous glucagon when hypoglycaemia is detected or predicted." (PMID 27364997, 2016). "In response to hypoglycaemia, glucagon was elevated before returning to basal levels." (PMID 26859145, 2016). "As plasma glucose falls below levels that can be reversed by responses at the level of pancreatic islets, i.e. suppression of insulin release and stimulation of that of glucagon, the brain’s sensing abilities are activated to allow timely detection of hypoglycemia." (PMID 26521082, 2016). "In contrast to the recently described effect of α cell-selective deletion of ZnT8 to enhance glucagon secretion at low glucose, we demonstrate that ZnT8 over-expression results in the suppression of glucagon release during hypoglycaemia, consequently enhancing glucose clearance." (PMID 27390586, 2016). "Moreover, selective downregulation of AMPK in the VMH caused impaired response to acute hypoglycemia by glucagon and epinephrine whereas local VMH application of AICAR during hypoglycemia amplified both glucagon and epinephrine levels." (PMID 27547453, 2016). "A 2-h intra-arterial infusion of either glucagon or epinephrine increased plasma concentrations (within the physiologic range experienced during acute hypoglycemia or stress (13, –, 15)) also raised plasma glucose by 5–8 mm with corresponding increases in plasma insulin." (PMID 27002151, 2016). "In DM, regulation of glucagon release is impaired with its levels inappropriately elevated at high glucose and reduced at low glucose, which might lead to fatal hypoglycemia." (PMID 27608006, 2016). "General conclusions based on commonly used experimental conditions may consequently overemphasize paracrine β-cell factors in the direct control of glucagon release in general and during hypoglycaemia in particular." (PMID 27044660, 2016). "This may in part be attributed to GABA-induced counter regulatory mechanisms, especially elevated glucagon, which prevent hypoglycemia in the face of increased insulin levels." (PMID 26617516, 2015). "Furthermore the risk of hypoglycaemia with GLP-1 is minimal, as both its stimulatory effect on insulin secretion and its inhibitory action on glucagon release switch off when ambient glucose levels are <4 mmol/L." (PMID 25848859, 2015). "Supporting a role of α-cell ATP in glucagon-mediated glucose counterregulation, [ATP]pm in α-cells was relatively more sensitive than that in β-cells, in response to the low glucose concentrations that characterize hypoglycemia." (PMID 25911612, 2015). "On the other hand, we would like to emphasize that the reduced incidence of hypoglycemia with an increased percentage of hyperglycemia could be also related to the preserved permanent glucagon response in WFS patients." (PMID 25916214, 2015). "There is also too little glucagon secretion at low glucose, which may precipitate fatal hypoglycemia." (PMID 25982967, 2015). "Animals exposed to recurrent hypoglycemia (RH and 2RH) had delayed glucagon responses." (PMID 25713330, 2015).
Hypoglycemia (continued). "Glucagon levels were significantly increased by hypoglycemia." (PMID 24594704, 2014). "A decrease in postprandial glucagon could reduce hyperglycemic excursions, while an increase in glucagon response following a hypoglycemia could reduce a hypoglycemic excursion." (PMID 25175981, 2014). "The cognitive alterations that can occur during hypoglycemia are not caused by the increased release of glucagon, adrenalin, noradrenalin, GH, and cortisol nor even by excess insulin." (PMID 24790575, 2014). "In addition, recurrent hypoglycemic episodes can weaken the adrenalin and glucagon response to decreased plasma glucose levels, and severe hypoglycemia can be induced." (PMID 25520819, 2014). "Surprisingly, serum glucagon levels in mutant mice under both fed conditions as well as after an overnight fast were similar to control littermates, pointing to a defective glucagon response, as persistent hypoglycemia should elicit an increase in circulating glucagon." (PMID 23977255, 2013). "Furthermore, when they induced hypoglycemia using a hypoglycemic clamp, the Sf1-Cre;Vglut2flox/flox mice displayed significantly blunted responses of counterregulatory hormones including glucagon and epinephrine." (PMID 23675313, 2013). "Hypoglycaemia could be sensed in the sNAc, and glucose homeostasis would be restored by the secretion of glucagon and stimulation of food consumption." (PMID 24339800, 2013). "Recently it has been suggested that glucagon might be responsible for both the hyperglycaemia and the occasional hypoglycaemia seen in diabetic patients." (PMID 24070224, 2013). "In apparent contradiction to our hypothesis identifying glucagon-producing cells as the culprit for hypoglycemia and postnatal lethality of islet-specific Vhlh mutant mice, transgenic mice with VHL inactivation specifically in α-cells survive to adulthood." (PMID 23977255, 2013). "However, in hypoglycemia, a decrease in β-cell secretion, in concert with a low α-cell glucose concentration, stimulates α-cell glucagon secretion." (PMID 23316165, 2012). "The role of glucagon in glucose homeostasis is well established; glucagon is produced by alpha cells of the pancreatic islets and increases glucose concentration in response to hypoglycaemia." (PMID 22899902, 2012). "Glucose stimulates glucagon release at low concentrations (hypoglycemia)." (PMID 22412861, 2012). "The i.p. infusion route has several desirable characteristics: reproducibility of insulin absorption, quick time to peak and return to baseline of insulin action, near-physiological peripheral insulin levels, and restoration of glucagon response to hypoglycemia and exercise." (PMID 24278682, 2012). "In addition to hypoglycemia, certain amino acids, in particular L-arginine stimulate glucagon secretion." (PMID 22162752, 2011). "This explains two main and characteristic clinical findings of neonatal HI: the high glucose infusion rate required to prevent hypoglycemia and the responsiveness of hypoglycemia to exogenous glucagon, since glucagon stimulates glycogen breakdown and gluconeogenesis." (PMID 21967988, 2011). "While this report has focused on modifying glucagon to achieve hypoglycemia resistance, a large number of other hormones and signaling peptides have short half-lives and may also be amenable to optimization by XTEN addition." (PMID 20418955, 2010). "The data show that Gcg-XTEN is effective in preventing hypoglycemia without the associated hyperglycemia expected for unmodified glucagon." (PMID 20418955, 2010). "The only currently approved drug for treatment of hypoglycemia is glucagon." (PMID 20418955, 2010). "In addition, she had previously experienced one episode of severe hypoglycemia (requiring a subcutaneous injection of glucagon by another person)." (PMID 17326710, 2007). "Thus, steroids, epinephrine, and glucagon appear to facilitate recovery from insulin-induced hypoglycaemia in a manner distinct from, but complementary to, the molecular clock." (PMID 15523558, 2004).
Hypoglycemia (continued). "This may contribute to the reduced glucagon response to hypoglycemia in type 1 diabetes." (PMID 40473678, 2025). "Few hypoglycemias in the next days could be treated with dextrose gel 40% or glucagon injection." (PMID 41438615, 2025). "Thus, patients receiving a GLP-1RA do not have inadequate glucagon secretion in response to hypoglycemia and are consequently not exposed to an increased risk for severe hypoglycemia." (PMID 40760325, 2025). "Characteristic parameters of T2DM include the following: rare ketoacidosis and hypoglycemia, usually mild hyperglycemia, decreased peripheral insulin sensitivity, normal or decreased hepatic insulin sensitivity, high levels of insulin and PP, normal or high glucagon levels, normal or low GLP-1." (PMID 39859258, 2025). "SSTR2a’s have also been shown to restore alpha-cell counterregulatory glucagon secretion in rodents subjected to antecedent hypoglycemia, suggesting that paracrine delta-cell somatostatin feedback inhibition on the alpha-cells increases with each recent bout of hypoglycaemia." (PMID 38612880, 2024). "In addition, glucagon administration has shown short-term benefits in alleviating hypoglycemia." (PMID 39219958, 2024). "In mouse models of insulin-induced hypoglycemia, intraperitonealadministration of glucagon-micelles successfully regulated blood glucoseconcentration, both reverting and preventing deep hypoglycemia dependingupon when the glucagon-micelles were injected relative to insulinadministration." (PMID 39634211, 2024). "The primary purpose of this study was to test the efficacy of two SSTR2 antagonists in a rodent model of T2D to see if treatment could enhance the endogenous glucagon counterregulatory response and prevent hypoglycemia during an insulin-induced hypoglycemic challenge." (PMID 38510652, 2024). "However, recurrent hypoglycemia induces increased GABA levels so that the absence of decreasing GABA concentrations during hypoglycemia is associated with a reduced glucagon and epinephrine response." (PMID 38397994, 2024). "In dogs that developed hypoglycemia after MVR, plasma glucagon levels were higher and serum insulin levels were lower than the preoperative levels, indicating that the cause of postoperative hypoglycemia did not appear to be hyperinsulinemia or hypoglucagonemia." (PMID 38393097, 2024). "When high-dose intravenous glucose is required, continuous intravenous infusion of glucagon as an additional therapy can help control hypoglycemia and prevent complications from fluid overload by reducing the rate of intravenous dextrose infusions required to prevent hypoglycemia." (PMID 37454648, 2024). "This could lead to insufficient glucagon and adrenaline release during hypoglycaemia." (PMID 37159865, 2023). "Hence, the observed effect of genipin on insulin sensitivity could be at least partially due to suppressed hypoglycemia-induced glucagon secretion from the islets, which needs further investigation." (PMID 36768454, 2023). "Moreover, sympathetic input to the α cell is required for the glucagon response to hypoglycemia." (PMID 38075070, 2023). "However, in infants, it presents with a clinical picture identical to that of hyperinsulinism (hypoglycemia associated with low/normal levels of ketone bodies and fatty acids, absence of metabolic acidosis and positive response to glucagon administration)." (PMID 37630734, 2023). "Therefore, the increase in intact GIP levels observed after inhibition of DPP4 may help maintain the counter-regulatory response of glucagon when glucose levels are controlled at hypoglycemia." (PMID 35630534, 2022). "In addition, Steinbusch and colleagues showed that ablation of GcK gene in VMHSF1 neurons impairs glucagon secretion in response to hypoglycemia, as well as a reduced parasympathetic and sympathetic nerve activation during 2-DG-induced glucopenia in female mice." (PMID 35619170, 2022).
Hypoglycemia (continued). "Thus, it needs a reliable control algorithm to combine multiple hypoglycemia prevention procedures such as initiation of glucagon when the blood glucose reaches the threshold (50–90 mg/dL), suspension and control insulin delivery, and escalation of alarms to remind the user." (PMID 36411933, 2022). "Given that the women attended the HNU, following an overnight fast, we expect that any hypoglycaemia over the period may have initiated a decrease in insulin secretion with a corresponding increase in glucagon to increase hepatic EGP via glycogenolysis and gluconeogenesis." (PMID 36584200, 2022). "GLP-1 RAs have its unique mechanism of action of simultaneously increasing insulin secretion and inhibiting glucagon only in response to increased glucose levels and can potentially be used in obese and nondiabetic individuals without the risk of hypoglycaemia." (PMID 36474714, 2022). "However, these HbA1c targets only apply if they can be achieved without a clinically important risk of severe hypoglycaemia, defined as events with symptoms of hypoglycaemia requiring help from another person to actively administer oral carbohydrate or inject glucagon or glucose." (PMID 36432552, 2022). "That circulating FFAs indeed blunt glucagon secretion through an Agpat5-dependent mechanism was confirmed by showing that the impaired glucagon response to hypoglycemia of AgRPAgpat5KO mice could be largely reverted when circulating free fatty acids were lowered by nicotinic acid treatment." (PMID 36180454, 2022). "Local glucopenia induced by infusion of 2-DG into rat VMH significantly increases glucagon levels in the circulation, associated with elevated blood glucose, whereas infusions of glucose directly into the VMH blocks glucagon release despite of the systemic hypoglycemia." (PMID 35619170, 2022). "Notably, the fluctuations in glucagon levels influencing hypoglycemia awareness and GV in such patients may be modulated by glucoregulatory peptides namely glucagon like peptide -1 (GLP-1), gastric inhibitory peptide-1 (GIP 1) which needs further studies." (PMID 35819935, 2022). "However, in insulinomas without somatostatin receptor expression, somatostatin analogs may worsen hypoglycemia by inhibiting counter-regulatory mechanisms, namely glucagon and growth hormone release." (PMID 35838801, 2022). "Whether the drop in glucose levels itself leads to copeptin secretion, or whether it mirrors other stimuli such as hypoglycemia-induced stress cannot be answered with our study and could be better defined in further research measuring glucagon and insulin levels throughout the stimulation tests." (PMID 35723775, 2022). "Some researchers are considering the impact of somatostatin antagonists or agents that suppress somatostatin secretion that could be used along with insulin therapy to restore a more appropriate release of glucagon during hypoglycemia and postprandial or fasting conditions." (PMID 36992764, 2022). "Thus, during insulin-induced hypoglycemia, glucagon secretion is increased due to GIP use." (PMID 35630534, 2022). "In fact, already some decades ago it was shown that glucagon levels increase at low glycemic levels with consequent stimulation of glycogenolysis and gluconeogenesis by the liver, indicating that such glucagon-based counter-regulation mechanisms are crucial for preventing hypoglycemia." (PMID 35057557, 2022). "Also, taking in some amino acids (via a protein source) may improve the release of glucagon and cognition during bouts of hypoglycemia." (PMID 36992764, 2022). "Thus, Agpat5 in AgRP neurons was required for normal hypoglycemia-induced glucagon secretion." (PMID 36180454, 2022). "Micro-doses of glucagon could be given at the same time as meal boluses of insulin to promote postprandial insulin absorption and larger doses of glucagon may be administered when indicated to treat and prevent hypoglycaemia." (PMID 36213069, 2022).
Hypoglycemia (continued). "It is well established that glucagon responses to hypoglycemia are severely impaired in type 1 diabetes but whether glucagon secretion is completely intact following other physiological and metabolic stressful stimuli compared with nondiabetic individuals has been less thoroughly investigated." (PMID 34405569, 2021). "While the intra islet insulin hypothesis might be an important component of iatrogenic hypoglycemia other regulatory mechanism within the islets exist including somatostatin from the delta cells inhibiting both glucagon and insulin secretion in a paracrine fashion." (PMID 34405569, 2021). "In T1D patients, dasiglucagon restored euglycemia after insulin-induced hypoglycemia at doses from 0.1 to 1.0 mg, and provided rapid and effective reversal of hypoglycemia in adults with T1D, with safety and tolerability similar to those reported for reconstituted glucagon injection." (PMID 34638984, 2021). "Similarly, the phenotype of PC2 is reduced growth and chronic hypoglycaemia caused by a lack of glucagon and insulin processing." (PMID 34187565, 2021). "We next investigated whether AVP stimulates glucagon secretion during hypoglycemia in vivo." (PMID 34787082, 2021). "The discrepancy between these results remains unclear but we speculate that the increased incidence of hypoglycemia in people on metformin and 100 mg vildagliptin daily during Ramaḍān may be related to interindividual variability in the glucagon response to hypoglycemia." (PMID 34305809, 2021). "This glucagon response appears to be preserved yet attenuated in individuals with type 1 diabetes compared with nondiabetic individuals, implying that glucagon release during exercise is activated by other regulatory pathways than those prevailing during hypoglycemia." (PMID 34405569, 2021). "Potentially women with T2D may be more susceptible to hypoglycemia as glucose substantially drops 2 h after an evening meal without a compensatory glucagon response." (PMID 32982972, 2020). "In addition to hypoglycemia, amino acids are known to play a pivotal role in glucagon secretion." (PMID 33424773, 2020). "However, compensatory glucagon production and gluconeogenesis to prevent hypoglycemia may at least partly explain these observations." (PMID 33096658, 2020). "Conversely, degradation of glucagon from alpha cells of the pancreas might result in hypoglycemia." (PMID 32051237, 2020). "Furthermore, our results suggest that a postprandial glucagon excursion preceding insulin peak might increase glucose levels at nadir, thus preventing hypoglycemia." (PMID 33424773, 2020). "Another school of thought could be that the extract at doses 400 and 800 mg/kg could have blocked the α cell of the islets of Langerhans from producing glucagon hormone, thus preventing stimulation of gluconeogenesis overnight, leading to the hypoglycemia seen at the zero hour before inoculation." (PMID 32030095, 2019). "Thus, GIP is known to stimulate glucagon secretion during hypoglycemia." (PMID 31275243, 2019). "The ease of use and the efficacy of IN glucagon reported in controlled or simulated studies have been confirmed in clinical studies where IN glucagon was administered to T1D adults and caregivers of T1D children to treat acute hypoglycemia episodes at home and in school settings." (PMID 31349701, 2019). "Interestingly, different from the previous case, also the minimum glucose level Gmin improves (increases) with Δ and Gmax: this is a consequence of the fact that we are using both insulin and glucagon as control inputs, which enables us to avoid both hypoglycemia and hyperglycemia." (PMID 30893335, 2019). "Therefore, the mechanism by which glucagon secretion is reduced in hypoglycemia is still controversial, although it may be partially explained by insulin resistance in pancreatic α cells." (PMID 31357734, 2019). "Thus, liver glycogen is essential for the protective effect of glucagon in hypoglycemia." (PMID 29595915, 2018).